CD46 (CD46 molecule)
Diseases named in the same sentence as CD46 in open-access papers (continued):
Sharing a sentence is not in itself a finding about the gene and the disease.
otosclerosis (2 papers, 2013 to 2023). Formation of spongy bone in the labyrinth capsule which can progress toward the stapes (stapedial fixation) or anteriorly toward the cochlea leading to conductive, sensorineural, or mixed hearing loss. "Specific diseases have not yet been attributed to CD46 isoform coexpression; however, present study supplies essential information about novel translated isoforms of CD46 emphasizing a potential association between isoform coexpression and otosclerosis." (PMID 23864959, 2013). "Various expressions of different splicing variants of CD46 seem to be one of the acceptable explanations for the genetic background of otosclerosis." (PMID 23864959, 2013). "The study herein presented provides evidence for the otosclerosis-associated expression pattern of CD46." (PMID 23864959, 2013). "Decreased serum level of anti-measles IgG is characteristic for otosclerosis, which is independent from vaccination or measles virus infection and can be determined by expression of otosclerosis-associated CD46 isoforms." (PMID 23864959, 2013). "Coexpression of novel os1, os2, os3, and os4 CD46 protein isoforms was exclusively associated to the histological diagnosis of otosclerosis in the ankylotic stapes footplates." (PMID 23864959, 2013). "In conclusion, we found a strong association between the expression of novel CD46 protein isoforms and histologically confirmed otosclerosis." (PMID 23864959, 2013). "Our results are consistent with four new splicing variants of CD46 mRNA being causally related to the viral pathogenesis of otosclerosis." (PMID 23864959, 2013). "The estimated molecular weights of os1–4 isoforms correlated with the mRNA sequence of otosclerosis-associated CD46 splicing variants reported earlier." (PMID 23864959, 2013). "Unique coexpression pattern of measles virus receptor (CD46) splicing isoforms in the human otic capsule is assumed, since otosclerosis is a measles virus-associated organ-specific disease." (PMID 23864959, 2013). "The answer may hide in the expression of different regulatory proteins of alternative splicing leading to a special expression pattern and altered functions of CD46 that could explain the organ-specific and virus-associated pathogenesis of otosclerosis." (PMID 23864959, 2013). "The present study investigates the coexpression pattern of CD46 protein isoforms in histologically proven otosclerotic, nonotosclerotic, and normal stapes footplates in order to establish organ-specific, otosclerosis-associated alternative splicing of the measles virus receptor CD46." (PMID 23864959, 2013). "Special expression pattern of CD46 isoforms due to organ-specific alternative splicing may explain genetically determined susceptibility for persisting measles virus infection observed in otosclerosis." (PMID 23864959, 2013). "As compared to these specimens, in otosclerosis (n = 50), four additional protein bands of CD46 isoforms were identified: os1, os2, os3, and os4 (27 kDa, 20 kDa, 17 kDa, and 14 kDa, resp)." (PMID 23864959, 2013). "It is supposed that the most important factor in the pathogenesis of otosclerosis is a consecutive autoimmune reaction due to continuous CD46-presented viral antigen stimulation of natural killer cells and CD8 positive T-lymphocytes." (PMID 23864959, 2013). "In order to identify CD46 involved in the pathogenesis of otosclerosis, we used representative groups of histologically diagnosed otosclerotic, nonotosclerotic, and normal stapes footplates (n = 109)." (PMID 23864959, 2013).
paroxysmal nocturnal hemoglobinuria (2 papers, 2020). Paroxysmal nocturnal hemoglobinuria (PNH) is an acquired clonal hematopoietic stem cell disorder characterized by corpuscular hemolytic anemia, bone marrow failure and frequent thrombotic events. "These include angioedema (C1 inhibitor [C1-INH] deficiency), kidney and eye diseases (FH, FI or CD46 deficiency), protein-losing enteropathy (CD55 deficiency) and paroxysmal nocturnal hemoglobinuria (PNH) (CD55 + CD59 deficiency)." (PMID 32064578, 2020).
peritonitis (2 papers, 2017 to 2023). Inflammation of the peritoneum (tissue that lines the abdominal wall and covers most of the organs in the abdomen). "Peritoneal biopsies were additionally evaluated for CD46, CD55, and CD59 expression depending on their history of PD-associated peritonitis." (PMID 28542228, 2017). "In peritoneal biopsy tissues obtained at PD catheter removal, we investigated the severity of peritonitis-associated peritoneal injuries and the expression of CRegs, CD46, CD55, and CD59 against peritoneal tissues without any episode of peritonitis." (PMID 37298097, 2023).
retinoblastoma (2 papers, 2020 to 2021). A malignant tumor that originates in the nuclear layer of the retina. "Typical features of MM cells, such as overexpression of CD46 and a dysregulated retinoblastoma pathway, enabled LOAd viruses to infect and kill a variety of MM cell lines, both in vitro and in vivo." (PMID 32355275, 2020).
Sepsis (2 papers, 2007 to 2023). Sepsis is defined as life-threatening organ dysfunction caused by a dysregulated host response to infection. "Importantly, in the CD46 transgenic mouse model, infection leads to sepsis and meningitis in adult mice without preinjection of enhancers, such as iron compounds." (PMID 17311106, 2007).
Stroke (2 papers, 2017 to 2025). Sudden impairment of blood flow to a part of the brain due to occlusion or rupture of an artery to the brain. "Although significant results were also identified for MERTK with both outcomes and for CD46 with stroke, their hazard ratios suggested opposite effects to those found in the MR analysis." (PMID 39818967, 2025). "Nonetheless, more data are needed to identify the threshold range of CD46 mRNA, miR-19, -20a, -185 and -374b for accurate diagnosis in stroke patients." (PMID 28199366, 2017). "Thus, it would be beneficial to investigate how the differential expression of CD46 contributes to the pathogenesis of the different stroke subtypes." (PMID 28199366, 2017).
Thrombocytopenia (2 papers, 2012 to 2021). A reduction in the number of circulating thrombocytes. "Patient 1 presented with hemolysis and thrombocytopenia and harbored a homozygous pathogenic CD46 change in the alternative complement system." (PMID 33712733, 2021).
uterine serous carcinoma (2 papers, 2015 to 2024). "The study found that uterine serous carcinoma is characterized by high levels of mCRPs CD46, CD55, and CD59." (PMID 39337406, 2024). "Consistent with this view, recent data from our group in uterine serous carcinomas, a subset of biologically aggressive tumors histologically similar to CS, demonstrate overexpression of mCRPs CD46, CD55 and CD59 in the majority of the tumors." (PMID 26474755, 2015).
abortion (1 paper, 2019). the ending of pregnancy by removing a fetus or embryo before it can survive outside the uterus. "Interestingly, increased complement activation has been recorded in human placentas following spontaneous abortion, while CD46 and CD55 (complement regulators) became reduced." (PMID 31395028, 2019).
acute coronary syndrome (1 paper, 2024). Signs and symptoms related to acute ischemia of the myocardium secondary to coronary artery disease. "The role of the complement inhibitory proteins CD46 and CD59 in the immune response to an acute coronary syndrome (ACS) is unknown." (PMID 39523332, 2024).
acute lymphocytic leukemia (1 paper, 2026). "The current study aims at investigating the expression levels of mCRPs; CD46 and CD55 in the acute lymphocytic leukemia and acute myelogenous leukemia and to further elucidate its role in Egyptian cancer patients." (PMID 41526546, 2026).
adenoma (1 paper, 1993). A neoplasm arising from the epithelium. "In the epithelial compartment of normal colorectal mucosa, of all adenomas, carcinomas and their liver metastases, CD46 was expressed throughout the epithelial compartment." (PMID 7692919, 1993).
Alport syndrome (1 paper, 2025). A rare renal disease characterized by glomerular nephropathy with hematuria progressing to end-stage renal disease (ESRD), frequently associated with sensorineural deafness, and occasionally with ocular anomalies. "One had a likely pathogenic heterozygous variant in the COL4A3 gene associated with Alport syndrome, and one had a heterozygous novel variant of uncertain significance in the CD46 gene associated with atypical hemolytic uremic syndrome (aHUS)." (PMID 41019761, 2025).
atypical teratoid rhabdoid tumor (1 paper, 2021). Atypical teratoid rhabdoid tumor (ATRT) is a highly malignant central nervous system (CNS) rhabdoid tumor (RT) found almost exclusively in children. "An attenuated measles virus is also under clinical investigation for children and young adults with recurrent medulloblastoma or atypical teratoid rhabdoid tumor (ATRT), which express the CD46 surface marker that mediate measles virus entry (NCT02962167)." (PMID 34277419, 2021).
B-cell NHL (1 paper, 2014). "High expression levels of membrane-bound complement regulatory proteins such as CD46 in tumors has been shown to suppress anti-tumor T-cell responses, and may inhibit anti-tumor therapeutic activity of monoclonal antibodies, including rituximab in B-cell NHL." (PMID 25294155, 2014).
bacterial meningitis (1 paper, 2013). Inflammation of the membranes surrounding the brain and spinal cord due to a bacterial infection. "The interaction with human CD46 represents a critical step for the onset of bacterial meningitis." (PMID 24107297, 2013).
bladder tumors (1 paper, 2018). "As a result, CAR expression was observed in 37 bladder tumors out of 59, whereas CD46 was observed in 29 bladder tumors." (PMID 30201920, 2018).
bullous pemphigoid (1 paper, 2018). Bullous pemphigoid (BP) is the most common form of autoimmune bullous dermatosis. "Our recent study demonstrated that loss of the inhibitory function of the complement regulator CD46 may be involved in the pathogenesis of bullous pemphigoid." (PMID 30473747, 2018).
Cachexia (1 paper, 2021). Severe weight loss, wasting of muscle, loss of appetite, and general debility related to a chronic disease. "Similarly, human hepatocytes are characterized by high expression of a battery of complement inhibitors, including CD46, CD55, CD59, and factor H, although it is not known whether their expression is stable in metabolic disorders such as obesity or cachexia." (PMID 34830921, 2021).
carcinoma in situ (1 paper, 2018). "However, multifocality, concomitant carcinoma in situ (CIS), intravesical chemotherapy, and recurrence did not statistically correlate with CD46 expression." (PMID 30201920, 2018).
cardioembolic stroke (1 paper, 2017). "This is as expected based on our observation that the expression of CD46 was higher in the non-cardioembolic stroke patients, and thus strongly supports our earlier findings that these miRNAs target CD46 mRNA." (PMID 28199366, 2017). "This study examined the microRNAs targeting cluster of differentiation 46 (CD46), a potential biomarker for cardioembolic stroke." (PMID 28199366, 2017). "In this study, we have shown that CD46 mRNA level to be significantly up-regulated in non-cardioembolic stroke while in cardioembolic stroke the CD46 mRNA level appears to be similar to that of the healthy controls." (PMID 28199366, 2017). "ROC curve showed that the miRNAs could distinguish cardioembolic stroke from non-cardioembolic stroke with better AUC value as compared to CD46." (PMID 28199366, 2017). "Hence, looking into miRNAs targeting CD46 can potentially uncover the differential pathway regulation between cardioembolic and non-cardioembolic stroke." (PMID 28199366, 2017). "Furthermore, miR-19, -20a, -185 and -374b have been demonstrated to target CD46 mRNA and these miRNAs also showed correspondingly inversed expression when compared to the expression of CD46 mRNA where the expression of the miRNAs were down-regulated in non-cardioembolic stroke." (PMID 28199366, 2017). "Thus, this study was aimed to identify the miRNAs targeting CD46 as they may serve as potential biomarkers and to uncover the mechanism behind differential expression of CD46 between cardioembolic and non-cardioembolic stroke." (PMID 28199366, 2017). "CD46 mRNA level was shown to be differentially expressed (p < 0.001) between cardioembolic stroke (median = 1.32) and non-cardioembolic stroke subtypes (large artery stroke median = 5.05; small vessel stroke median = 6.45)." (PMID 28199366, 2017). "In brief, we have verified that CD46 mRNA is differentially expressed between cardioembolic stroke and non-cardioembolic stroke subtypes, where it was up-regulated in non-cardioembolic stroke." (PMID 28199366, 2017). "Among these mRNAs, there was an inhibitor of complement cascade, cluster of differentiation 46 (CD46), which could distinguish cardioembolic stroke from non-cardioembolic stroke subtype." (PMID 28199366, 2017). "Thus, it is important to identify the miRNAs that target CD46 mRNA in order to demonstrate the potential of using miRNAs as biomarkers to distinguish cardioembolic stroke from non-cardioembolic stroke." (PMID 28199366, 2017). "This seems to suggest that the deregulation of the complement cascade, involving CD46 and miRNAs targeting CD46 (miR-19a, -20a, -185 and -374b) may be potential markers for the differential regulation of coagulation cascade between cardioembolic stroke and non-cardioembolic stroke." (PMID 28199366, 2017).
colon adenocarcinoma (1 paper, 2018). "Human CD46 was cloned from DLD human colon adenocarcinoma cells into a self-inactivating lentiviral genome, which was rescued by cotransfection with packaging plasmids." (PMID 29898782, 2018).
colorectal tumors (1 paper, 2016). "In this study, we show that CD46 is highly expressed in most colorectal tumors, when compared to matching normal mucosa." (PMID 27203670, 2016).
cutaneous melanoma (1 paper, 2020). A primary melanoma arising from atypical melanocytes in the skin. "All the immunohistochemical staining of primary cutaneous melanoma lesions from five patients indicated positive CD46 expression, whereas CAR expression could not be detected." (PMID 32486014, 2020).
dilated cardiomyopathy (1 paper, 2012). Cardiomyopathy which is characterized by dilation and contractile dysfunction of the left and right ventricles. "Our previous studies on adenoviral receptor expression in human heart tissue suggested that the native Ad5 capsid configuration would be better suited for cardiac gene transfer than Ad5/35 vectors as CAR had higher levels of expression than CD46 in both normal and dilated cardiomyopathy hearts." (PMID 23190872, 2012). "Previously we have reported an analysis of various Ad receptors in both human dilated cardiomyopathy (DCM) hearts and non-DCM hearts demonstrating significant differences in expression patterns of CAR and CD46, with CAR receptor demonstrating higher expression in both DCM and non-DCM hearts." (PMID 23190872, 2012).
epidemic keratoconjunctivitis (1 paper, 2024). Keratoconjunctivitis resulting from infection by adenoviruses. "Based on sequence similarity between the fiber proteins of adenoviruses associated with epidemic keratoconjunctivitis, we hypothesized that HAdV-D64 would use the same receptors, sialic acid and CD46, to adhere to the cell surface as HAdV-D37." (PMID 39772136, 2024).
gastric cancer (1 paper, 2022). A primary or metastatic malignant neoplasm involving the stomach. "For instance, negative regulators of complement (such as CD46, CD55, and CD59) have been found to be highly expressed in gastric cancers, which could potentially explain why T+P therapies failed to offer a significant clinical benefit in the JACOB Phase III trials of gastric HER2+ cancers." (PMID 35167491, 2022).
HCMV infection (1 paper, 2024). "The upregulation of CD55, CD46, and CD59 during HCMV infection in cells is notable, given that all three host proteins serve unique functions in regulating complement at various stages of the complement cascade and in multiple pathways." (PMID 39066333, 2024). "While some complement proteins such as CD46 may facilitate HCMV infection, other studies have reported a possible protective role of other complement proteins such as MBL in inhibiting HCMV infection." (PMID 39066333, 2024).
IgA nephropathy (1 paper, 2018). "Moreover, higher transcripts of CD46, CD55, CD59, and CFI were observed in recurrent IgAN nephropathy than in native kidney IgA nephropathy." (PMID 30356754, 2018).
iron overload (1 paper, 2020). "P26 carried HAMP and HFE variations probably explaining iron overload and CD46 variation for susceptibility to hemolysis." (PMID 32641076, 2020).
ischemic stroke (1 paper, 2017). A stroke disorder caused by obstruction of blood flow to the brain, due to thrombotic (local blood clot formation) or embolic (due to a blood clot or other material traveling from another site) event. "Among these 40 mRNAs, CD46 seems to have a direct involvement in the pathophysiology of different ischemic stroke subtypes." (PMID 28199366, 2017). "This is not surprising as CD46 is part of the complement cascade which regulates inflammation, a crucial pathological process in the pathophysiology of ischemic stroke." (PMID 28199366, 2017).
kidney failure (1 paper, 2025). An acute or chronic condition that is characterized by the inability of the kidneys to adequately filter the blood. "Out of the 20 patients who developed kidney failure, nine had genetic forms of aHUS (four CFH, three CFI, one CD46, and one C3 mutation) and 11 had no identified cause, including six without genetic testing and five with negative genetic screening results (not shown)." (PMID 40224677, 2025).
leprosy (1 paper, 2019). Leprosy is a chronic infectious disease affecting primarily the skin and peripheral nervous system. "Additionally, we observed that a classification of leprosy patients is possible using transcriptomics since a set of genes were increased in BL/LL patients (CD46, CXCL10, FCGR1A, HDAC2 and TLR4) and TT/BT showed a higher expression of IL2 and TLR6." (PMID 31784594, 2019).
leukoplakia (1 paper, 2025). A white patch or plaque on a mucous membrane that cannot be characterized clinically or pathologically as any other disease. "In oral leukoplakia, CD46 expression is upregulated, membrane expression is enhanced in areas of abnormal epithelial hyperplasia, TREM1 expression is elevated, inflammatory cell infiltration is present, and LC3B/ATG5 expression is low." (PMID 41415031, 2025). "Compared to normal tissue, CD46 and TREM1 scores were significantly elevated in inflammatory, leukoplakia, and OSCC tissues (P < 0.05)." (PMID 41415031, 2025). "H-Score semi-quantitative analysis revealed that compared to normal tissue, both CD46 and TREM1 expression scores were significantly elevated in leukoplakia and OSCC tissues (P < 0.05), peaking in OSCC." (PMID 41415031, 2025).
lung fibrosis (1 paper, 2025). "Increased C3a levels also upregulate TGF-β, a key mediator of obliterative bronchiolitis, which downregulates membrane regulatory proteins such as CD46/Crry and CD55 in models of lung fibrosis." (PMID 41217841, 2025).
lymphopenia (1 paper, 2012). Reduction in the number of lymphocytes. "Compared with healthy controls, we observed in SLE patients with lymphopenia and neutropenia decreased expression of CD55, CD59, and CD46 (P < 0.05)." (PMID 22761633, 2012).
meningococcal meningitis (1 paper, 2021). "Additionally, levels of several complement regulators (CD35, CD46, CD55 and CD59) were shown in the CP of patients who suffered from meningococcal meningitis." (PMID 34425919, 2021).
mesenchymal tumors (1 paper, 2025). "HVEM and CD46 also demonstrated significant upregulation patterns across various epithelial and mesenchymal tumors." (PMID 41210942, 2025).